XPO5 (exportin 5)
Diseases named in the same sentence as XPO5 in open-access papers (continued):
Sharing a sentence is not in itself a finding about the gene and the disease.
tumor (39 papers, 2012 to 2025). "Among these, Hsp90ab1 and XPO5 have been previously associated with poor prognosis and tumor-suppressor properties in GC." (PMID 32849808, 2020). "In addition, the rs3742330 of DICER1, rs784567 of TARBP2, rs417309 of DGCR8, and rs14035 of RAN as well as rs11077 of XPO5 are associated with the LC progression depending on the tumor size." (PMID 26688807, 2015). "Furthermore, the DGCR8 rs1640299, DICER1 rs3742330 and rs13078, RAN rs14035, and XPO5 rs11077 as well as rs784567 of TARBP2 genes single nucleotide polymorphisms have demonstrated an association with tumor progression depending on the lymph node metastases." (PMID 26688807, 2015). "Additionally, rs417309 of DGCR8, rs3742330 and rs13078 of DICER1, and rs784567 of TARBP2 as well as rs11077 of XPO5 are associated with the progression of LC depending on the tumor size and lymph node metastases." (PMID 26688807, 2015). "Silencing XPO5 can effectively attenuate the tumor-promoting effect of serum exosomes in TNBC patients." (PMID 40657248, 2025). "Our study shows that XPO5 expression is significantly elevated in tumor tissues compared with normal tissues." (PMID 40657248, 2025). "PP2Ac is capable of dephosphorylating XPO5 at Ser416, regulating XPO5's ability to transport pre‐miRNA and promoting the expression of tumor‐suppressing miRNAs." (PMID 39399646, 2024). "Several intermediaries of miRNA biosynthesis, including Drosha, Dicer, TRBP, and XPO5, can exhibit tumor suppressor and oncogenic behavior depending on their status and the tumor type in which they are expressed." (PMID 37104009, 2023). "Further augmentation of PP2A restored the cytoplasmic distribution of XPO5 and promoted the expression of several tumor‐suppressive miRNAs." (PMID 35441157, 2022). "Our findings found that PP2A‐mediated dephosphorylation of XPO5 restored the biogenesis of several important tumor‐suppressive miRNAs (e.g., miR‐122 and miR‐200b) via antagonizing ERK kinase." (PMID 35441157, 2022). "We found that XPO5 mRNA expression levels were significantly increased in the tumor tissues compared to the normal tissues (P = 1.50E-20 and P = 5.27E-11, respectively)." (PMID 32127945, 2020). "We observed significant over-expression of ADAR, ADARB1, DDX5/17/20, DGCR8, DICER1, DROSHA, EIF2C1-4 (AGO1-4), GEMIN4, POLR2A, TARBP2, TNRC6A and XPO5 in tumor tissue compared to adjacent mucosa." (PMID 31510013, 2019). "Due to its PIN1-inhibitory activity, API-1 has been found to increase XPO5-mediated pre-miRNA export from the nucleus to the cytoplasm and restore biosynthesis of tumor suppressive miRNAs in HCC cells." (PMID 32010690, 2019). "The expression level of XPO5 is up-regulated in urothelial carcinoma of the bladder and breast cancer and is positively correlated with tumor development and invasion." (PMID 24904827, 2014). "The nuclear export of pre-miRNAs mostly relies on XPO-5, whose damage in tumor cellsmay result in global downregulation of mature miRNAs." (PMID 25012758, 2014). "XPO5-inactivating mutations are always observed in many human tumors,indicating that XPO5 is a candidate haplo-insufficient tumor-suppressor gene." (PMID 25012758, 2014). "Inhibition of XPO5 effectively weakens the pro-tumor effects of TNBC patient serum exosomes." (PMID 40657248, 2025). "Silencing XPO5 can effectively inhibit the tumor-promoting effect mediated by lncRNA SNHG4." (PMID 40657248, 2025). "Additionally, miR‐200b, a frequently downregulated tumor suppressor in a variety of tumors, was also elevated by B55β‐induced XPO5 dephosphorylation." (PMID 35441157, 2022). "AUNIP, FANCI, LASP1, PSMD8, and XPO5 are putative tumor antigens for mRNA vaccine development." (PMID 35846349, 2022). "Importantly, p‐XPO5 was downregulated, whereas miR‐122 and miR‐200b were elevated in SK‐Hep1 B55β tumor, indicating that B55β exerts in vivo anti‐HCC role through dephosphorylating XPO5 and promoting some miRNA expression." (PMID 35441157, 2022).
tumor (continued). "In addition, Pin1 also activates many pro-proliferative proteins to enhance tumor cell proliferation and tumor growth, including c-Myc and XPO5." (PMID 32296699, 2020). "In addition, the expression of DDX5/20, DGCR8, DICER1, DROSHA, EIF2C1-4, GEMIN4, TNRC6A and XPO5 was deregulated not only in tumor tissue, but also in corresponding liver metastases compared to adjacent tissue." (PMID 31510013, 2019). "In a xenograft animal model, silencing XPO5 also significantly attenuates tumor growth." (PMID 29723684, 2018). "The restoration of XPO5 repairs the impaired export and expresses tumor suppressor features." (PMID 24904827, 2014). "Sex and age were not statistically significant predictors of post-operative survival time; however, tumor size, tumor stage, child classification, portal vein thrombosis and rs11077 SNP site located in XPO5 3′UTR were correlated with survival time in these patients." (PMID 24676133, 2014). "Additionally, compared with the adjacent tissues, the expression level of XPO5 was increased in TNBC tumor tissues, suggesting that XPO5 high expression may contribute to TNBC progression." (PMID 40657248, 2025). "Farrerol might also regulate tumor suppression by targeting XPO5." (PMID 37012254, 2023). "Lack of XPO5 expression and mutated forms of XPO5 are both highly correlated with reduced levels of miRNAs and their inhibitory targets; restoring functional XPO5 seemed to act as a tumor suppressor." (PMID 37373948, 2023). "Taken together, the expression of these tumor‐suppressive miRNAs is negatively correlated with the level of XPO5 phosphorylation, and the regulatory B55β subunit could antagonize the effect of ERK kinase on XPO5, thereby promoting the expression of these miRNAs." (PMID 35441157, 2022). "Additionally, the role of Exportin 5 (XPO5) in tumor progression has been under investigation." (PMID 30018188, 2018). "A total of five potential tumor antigens correlated with prognosis and infiltration of antigen-presenting cells, including AUNIP, FANCI, LASP1, PSMD8, and XPO5 were identified." (PMID 35846349, 2022). "In this study, we identified five tumor antigens (AUNIP, FANCI, LASP1, PSMD8, and XPO5) that were considered promising candidates as mRNA-based vaccines." (PMID 35846349, 2022). "Tumor MVs contain complexes of ARF6/XPO5 and pre-miRs; translocation of XPO5 to the MVs involve a complicated interaction involving CK2, RAN and cytohesion family guanine exchange factors." (PMID 39698114, 2020). "By impairing pre-miRNA binding capacity of XPO5, PIN1 has been found to reduce the expression of tumor suppressive miRNAs, such as miR-122, miR-200b, and miR-146a." (PMID 32010690, 2019). "Several components of the miRNA biogenesis machinery (XPO5, DICER and TRBP) have been shown to act as haploinsufficient tumor suppressors." (PMID 23977393, 2013). "Several mechanisms have been determined to influence cargo selection in EVs, notably the ADP-ribosylation factor 6 (ARF-6)-Exportin-5 axis, where ARF6-GTP interacts with Exportin-5 to deliver miRNA into tumor microvesicles (MVs) in an ARF6-GTP dependent manner." (PMID 36467419, 2022). "The expression of some RBPs (such as XPO5 and CPEB3) showed significant differences between the early stage and the advanced stage, and this difference was consistent with the changing trend between normal tissues and tumor tissues." (PMID 35036125, 2021). "Therefore, immunotherapy using mRNA vaccines targeting previously recognized tumor antigens (AUNIP, FANCI, LASP1, PSMD8, and XPO5) could induce immune cell infiltration to reinvigorate the ISI patient’s immune system." (PMID 35846349, 2022). "Since the level of protein expression of at least three miRNA machinery components, Dicer, Drosha and XPO5, was positively correlated with the radioresistance of NSCLC cells, the high level of their expression may contribute to the tumor cells’ response to treatment in a miRNA-guided fashion." (PMID 22479364, 2012).
infection (8 papers, 2017 to 2024). The state of being infected such as from the introduction of a foreign agent such as serum, vaccine, antigenic substance or organism. "The three cell types were infected with the SARS-CoV-2 delta variant at an MOI of 0.1, and mRNA expression levels of AGO2, DICER1, DGCR8, DROSHA, and XPO5 were measured 24 h and 48 h after infection." (PMID 37243263, 2023). "The results showed that infection of NHBE and Calu-3 cells with SARS-CoV-2 did not impact mRNA expression levels of AGO2, DICER1, DGCR8, DROSHA, and XPO5 at 24 and 48 h post infection, in good concordance with our results on patient samples." (PMID 37243263, 2023). "Second, the western blot results showed that Dicer protein expression was abolished after infection, while a decreased level of XPO5 was observed." (PMID 34915931, 2021). "However, in Vero E6 cells, AGO2, DICER1, DGCR8, and XPO5 mRNA levels were slightly upregulated 24 h after infection with SARS-CoV-2." (PMID 37243263, 2023). "Also, differential expression of putative Argonaute, Drosha, Piwi, Exportin-5 and Tudor genes at different snail developmental stages and during infection with S. mansoni were observed." (PMID 32328235, 2020). "Our study showed differential expression of putative Argonaute, Drosha, Piwi, Exportin-5 and Tudor genes at different snail developmental stages and during infection with S. mansoni, suggesting that the machinery is required for miRNA and piRNA processing in B. glabrata at all stages." (PMID 28719649, 2017). "On the other hand, infection of Vero E6 cells with SARS-CoV-2 impacted mRNA levels of AGO2, DICER1, DGCR8, and XPO5 at 24 h." (PMID 37243263, 2023). "Another example is that infection with Kaposi’s sarcoma-associated herpesvirus (KSHV) resulted in increased expression of DICER1 mRNA in primary human umbilical vein endothelial cells, whereas mRNA expression levels of DGCR8, DROSHA, and XPO5 did not change significantly." (PMID 37243263, 2023).
renal diseases (1 paper, 2022). "The function of XPO5 has been associated with the SMAD signaling pathway in relation to kidney disease previously." (PMID 36371311, 2022). "Besides, XPO5 interacts with several nucleoporins such as NUP107, NUP93 and NUP205 directly or indirectly during the cargo process, which has been associated with kidney diseases." (PMID 36371311, 2022). "Exportin 5 (XPO5) plays a specific role in the nucleocytoplasmic transport of double-stranded RNA binding protein Staufen2 and pre-miRNAs, which are important in the regulatory cascade of kidney development, maintenance of renal function, and progression of renal diseases." (PMID 36371311, 2022).
XPO5 also shares sentences with these, for which no sentence is quoted: esophageal cancer (5 papers); non-small cell lung carcinoma (4); lung adenocarcinoma (2); Adult onset (1); autism (1); esophageal squamous cell carcinoma (1); immune deficiency (1); leukemia (1); lymphoma (1); movement disorder (1); noise induced hearing loss (1); overgrowth syndrome (1); pancreatic cancer (1); pediatric cancers (1); prostate adenocarcinoma (1); pulmonary fibrosis (1); renal carcinoma (1); thyroid neoplasms (1); triple-negative breast carcinoma (1).